ZFP57 (ZFP57 zinc finger protein)
Diseases named in the same sentence as ZFP57 in open-access papers (continued):
Sharing a sentence is not in itself a finding about the gene and the disease.
liver cancer (1 paper, 2023). An epithelial or non-epithelial malignant neoplasm that arises from the liver. "ZFP57 and ZNF605 demonstrate binding to a significant number of LTR12C elements present in liver cancer PMDs, suggesting that binding of these KZFPs could maintain the methylation at LTR12Cs." (PMID 37470704, 2023).
lymph node metastasis (1 paper, 2019). "The correlation between ZFP57 expression level and clinical features, including age, tumour size, T grade, lymph node metastasis, receptor status and Ki67 was also studied." (PMID 30787268, 2019).
neuroblastoma (1 paper, 2024). Neuroblastoma (NB) is the most common solid, extracranial childhood tumor. "We have shown that the alternative 5’ promoter of ZFP57 can be found in neural tissues such as neuroblastoma cells." (PMID 39681839, 2024). "The neuroblastoma cell line represented a tissue that expresses ZFP57 at higher quantities, providing more biologically relevant results." (PMID 39681839, 2024).
serous ovarian carcinoma (1 paper, 2023). "Therefore, we speculate that ZFP57 may be a good prognostic marker of high-grade serous ovarian cancer." (PMID 37497403, 2023).
Temples’ syndrome (1 paper, 2024). "In mice, ZFP57 plays the predominant role in the maintenance of imprinting, whereas, in its absence, ZFP445 is required to preserve methylation in a subset of imprinting control regions such as those present in the MEG3/DLK1:IG-DMR, that involved in Temples’ syndrome." (PMID 38909248, 2024).
teratocarcinoma (1 paper, 2019). A germ cell tumor characterized by the presence of an embryonal carcinoma component and a teratoma component. "As a member of KRAB-ZFPs, ZFP57 was originally identified as an undifferentiated cell-specific gene when cloned from a mouse teratocarcinoma stem cell line, F933." (PMID 30787268, 2019).
cancer (9 papers, 2015 to 2023). A tumor composed of atypical neoplastic, often pleomorphic cells that invade other tissues. "However, how loss of ZFP57 or TRIM28 function is related to extensive hypomethylation in imprinted loci in cancer cells is currently unknown." (PMID 26473022, 2015). "The zinc finger protein 57 (ZFP57) plays crucial functions during the progression of cancer and is reported as a prognostic and therapeutic candidate in a variety of cancer." (PMID 37497403, 2023). "In both mESCs and human cancer cells, overexpression of NANOG resulted in increased expression of ZFP57, while its silencing caused ZFP57 down-regulation." (PMID 37492743, 2023). "Therefore, our investigations broaden the knowledges regarding the expression pattern, oncogenic roles, and cellular mechanism of ZFP57 in human cancers." (PMID 37497403, 2023). "ZFP57 can inactivate the Wnt/β-catenin pathway and inhibit cancer cell proliferation." (PMID 36276285, 2022). "Taking into account the observations that ZFP57 regulates multiple imprinted and non-imprinted loci, it may be hypothesized that also other genes may have a key role in ZFP57-mediated influence on cancer biology." (PMID 33672287, 2021). "The available data indicate both TSG and oncogenic functions of ZFP57 in different cancer models." (PMID 33672287, 2021). "However, there are few reports on the role of ZFP57 in radioresistance of cancers." (PMID 36276285, 2022). "Similar to ZFP57, our data demonstrate that the level of ZNF10 is not related to KIRC patients’ survival, although it is negatively associated with cancer stemness." (PMID 34638319, 2021).
tumor (8 papers, 2019 to 2026). "In addition, knockdown of ZFP57 gene caused suppression of HT1080 tumor formation while overexpression of the gene enhanced tumor formation in immunocompromised mice." (PMID 31245293, 2019). "In xenografts, ZFP57 overexpression increased tumor growth and impaired radioiodine retention, whereas Res suppressed ZFP57, restored differentiation, enhanced radioiodine avidity, and inhibited glycolysis." (PMID 41761234, 2026). "For example, ZFP57 was found to play a tumor suppressor role through inhibiting Wnt/β-catenin signaling pathway." (PMID 40612670, 2025). "Recently, several studies have confirmed that ZFP57 plays important roles in tumor initiation, development and metastasis." (PMID 37497403, 2023). "A large number of reports have been published regarding the role of ZFP57 in tumor cell proliferation." (PMID 36276285, 2022). "Twenty-six days after inoculation, the volumes and weights of tumours infected with SUM1315 cells which overexpressed ZFP57 were smaller than those of the control group." (PMID 30787268, 2019). "The discovery of abnormal expression and tumor related function of ZFP57 in OC indicated it may become a new diagnosis-related biomarker and a therapeutic protein in the treatment of OC." (PMID 37497403, 2023). "As an important member of KRAB-ZFPs, it is likely that ZFP57 could inhibit tumour proliferation through the Wnt/β-catenin pathway." (PMID 30787268, 2019). "ZFP57 has also been previously reported to induce IGF2 expression and subsequently promote the growth of tumor cells." (PMID 37497403, 2023).
ZFP57 also shares sentences with these, for which no sentence is quoted: psychiatric disorder (2 papers); rheumatoid arthritis (2); Arthritis (1); autism spectrum disorder (1); cardiovascular disease (1); central precocious puberty (1); clear cell ovarian cancer (1); cognitive decline (1); coronary heart disease (1); COVID-19 (1); Crohn disease (1); depression (1); endometrioid ovarian cancer (1); fibrosarcoma (1); hyperglycaemia (1); Hypertension (1); Insulin resistance (1); liver diseases (1); macroglossia (1); metabolic syndrome (1); metastatic tumor (1); mucinous ovarian cancer (1); multiple sclerosis (1); myeloid malignancies (1); neurodegenerative disease (1); Obesity (1); Ovarian cyst (1); ovarian serous cystadenocarcinoma (1); periodontitis (1); persistent foramen ovale (1).
A further 4 diseases each share a sentence with ZFP57 in 1 paper.